NTPCR (nucleoside-triphosphatase, cancer-related)
Description:
Has nucleotide phosphatase activity towards ATP, GTP, CTP, TTP and UTP. Hydrolyzes nucleoside diphosphates with lower efficiency.
Synonyms: C1orf57; MGC13186; HCR-NTPase; THEP1
Tractability: Small molecule: it has a high-quality binding pocket. PROTAC: ubiquitination databases record sites on it; its protein half-life has been measured.
Target class: Enzyme; Hydrolase
Gene: Protein-coding gene on chromosome 1 (232,950,564 to 232,983,882, forward strand). Ensembl gene ENSG00000135778.
Subcellular location (Human Protein Atlas): Cytosol
Gene Ontology:
Molecular function: ATP hydrolysis activity; CTPase activity; GTPase activity; ribonucleoside triphosphate phosphatase activity; RNA binding
Cellular component: membrane; mitochondrion
Genetic constraint (gnomAD): Loss-of-function variants: 11 observed, 14.55 expected, observed/expected ratio (o/e) 0.76, 90% interval 0.47 to 1.25. The upper end of that interval is the gene's LOEUF score, 1.25, which puts it in group 5 of 6, group 1 being the genes least tolerant of losing a copy. Missense variants: 196 observed, 234.87 expected, observed/expected ratio (o/e) 0.83, 90% interval 0.74 to 0.94. Synonymous variants: 86 observed, 93.04 expected, observed/expected ratio (o/e) 0.92, 90% interval 0.78 to 1.11.
Homologues: Orthologues: macaque NTPCR (98% identical), rabbit NTPCR (93% identical), chimpanzee NTPCR (91% identical), pig NTPCR (88% identical), guinea pig NTPCR (84% identical), dog NTPCR (83% identical), mouse Ntpcr (82% identical), rat Ntpcr (76% identical), zebrafish ntpcr (63% identical), tropical clawed frog ntpcr (59% identical), Drosophila melanogaster CG10581 (43% identical).
Diseases named in the same sentence as NTPCR in open-access papers:
NTPCR is named in the same sentence as 5 diseases in open-access papers, as found by Europe PMC text mining. Sharing a sentence is not in itself a finding about the gene and the disease.
NTPCR shares sentences with these, for which no sentence is quoted: cancer (1 paper); cholangiocarcinoma (1); liver (1); neuroblastoma (1); tumour (1).